MC4R (melanocortin 4 receptor)
Diseases named in the same sentence as MC4R in open-access papers (continued):
Sharing a sentence is not in itself a finding about the gene and the disease.
Hepatic steatosis (22 papers, 2015 to 2026). Steatosis is a term used to denote lipid accumulation within hepatocytes. "In this respect, we have shown that genetically obese melanocortin 4 receptor (Mc4r)-deficient mice on a high-fat diet progressively develop hepatic steatosis, NASH, and multiple liver tumors." (PMID 36678220, 2023). "Here, we used Western diet-fed melanocortin 4 receptor-deficient mice that have similar phenotypes to nonalcoholic steatohepatitis patients including progressively developed hepatic steatosis as well as fibrosis." (PMID 31990961, 2020). "In this study, we examined the effects of OCA on the development of NASH using melanocortin 4 receptor-deficient (MC4R-KO) mice that progressively developed hepatic steatosis and NASH on Western diet (WD)." (PMID 29802399, 2018). "In addition, hepatic FASN deficiency ameliorated hepatic steatosis to a lesser extent in Mc4r-KO mice than in ob/ob mice, as assessed on the basis of hepatic triglyceride content (70% versus 96% inhibition)." (PMID 37681411, 2023). "Vehicle-treated WD-fed MC4R-KO mice showed an increase in these scores and a prominent increase in liver steatosis." (PMID 41266634, 2025). "They demonstrated that EPA treatment effectively prevents the development and progression of liver fibrosis in MC4R-KO mice, and hepatic steatosis reduced significantly." (PMID 35685520, 2022). "In conclusion, we have demonstrated that anagliptin prevents fibrogenesis and carcinogenesis in the liver of MC4R-KO mice fed WD, but only marginally affecting body weight, systemic glucose and lipid metabolism, and hepatic steatosis." (PMID 31969650, 2020). "In conclusion, we demonstrated that ACC1/2 liver-targeted dual inhibition not only improved hepatic steatosis but also suppressed fibrosis progression in WD-fed MC4R KO mice with severe hepatic steatosis and fibrosis." (PMID 31990961, 2020). "We confirmed that MC4R-KO mice showed hepatic steatosis and liver fibrosis after 10 and 20 weeks of WD feeding, respectively." (PMID 31969650, 2020). "We generated MC4R KO mice and evaluated the effects of GS-0976 on hepatic steatosis and fibrosis in WD-fed MC4R KO mice." (PMID 31990961, 2020). "Treatment with OCA effectively prevented chronic inflammation and liver fibrosis in WD-fed MC4R-KO mice with only marginal effect on body weight and hepatic steatosis." (PMID 29802399, 2018). "Collectively, EPA treatment effectively prevents the development and progression of NASH in MC4R-KO mice along with amelioration of hepatic steatosis." (PMID 25816330, 2015). "Accordingly, MC4R-KO mice would provide a novel rodent model with which to investigate the progression from diet-induced hepatic steatosis to NASH." (PMID 25816330, 2015). "In conclusion, we demonstrate that EPA treatment effectively prevents the development and progression of liver fibrosis in MC4R-KO mice along with marked reduction of hepatic steatosis." (PMID 25816330, 2015). "RESULTS: WD-fed MC4R-KO mice exhibited significant hepatic steatosis, inflammation, and fibrosis." (PMID 41742234, 2026). "In this study, we found that treatment with anagliptin effectively prevented inflammation, fibrosis, and carcinogenesis in the liver of MC4R-KO mice fed WD, while only marginally affecting body weight, systemic glucose and lipid metabolism, and hepatic steatosis." (PMID 31969650, 2020). "In addition to the known phenotypes, such as obesity and insulin resistance, MC4R-KO mice on high-fat diet or Western diet (WD) progressively exhibit hepatic steatosis, NASH and multiple liver tumors." (PMID 29802399, 2018).
Hepatic steatosis (continued). "Correspondingly, CANA also attenuated hepatic steatosis in WD-fed MC4R-KO mice, after treatment for eight weeks, along with healthy adipose expansion, suggesting that the preventive effect on hepatic steatosis was due to the class effect(s) of SGLT2 inhibitors." (PMID 29402900, 2018). "In addition, we did not see an increased prevalence of hepatic steatosis in the phenome-wide association study of people with LoF MC4R variants in the UK Biobank." (PMID 41102563, 2025). "Therefore, MC4R deficiency led to liver steatosis but did not cause significant change in kidney histology." (PMID 27713523, 2016). "Compared with Mc4r-KO F/F mice, Mc4r-KO HKO mice showed a similar BW and food intake as well as attenuated hepatic steatosis and glucose intolerance." (PMID 37681411, 2023). "Hepatic FASN deficiency may also alter lipid profiles and lipoprotein metabolism, and such effects may contribute to the fasting hypercholesterolemia apparent in ob/ob HKO mice and to the amelioration of hepatic steatosis in ob/ob HKO and Mc4r-KO HKO mice." (PMID 37681411, 2023). "Our study demonstrated that WD-fed MC4R KO mice had many characteristics in common with NASH patients, such as hepatic steatosis, increased Sirius Red-positive area, hepatic hydroxyproline content, fibrosis-related gene expression in the liver and plasma liver enzyme levels." (PMID 31990961, 2020). "An eight-week CANA treatment attenuated hepatic steatosis in WD-fed MC4R-KO mice, with increased epididymal fat mass without inflammatory changes." (PMID 29402900, 2018). "Moreover, it is commonly believed that the Mc4r-/- mice are considered as an appropriate model of non-alcoholic fatty liver disease with its typical features, such as the hepatic steatosis and the increased activity of the pro-inflammatory and apoptotic factors." (PMID 30870482, 2019).
morbid obesity (19 papers, 2009 to 2024). An excess of body weight, normally defined as an individual with a body mass index greater than 35 or a body weight greater than one hundred percent of ideal body weight. "Clinical neuropathy has been reported in a 27-year old male with a MC4R gene mutation and morbid obesity, but this was attributed to the presence of T2DM." (PMID 38974580, 2024). "We identified two novel heterozygous variants, c.253A>G p.Ser85Gly and c.802T>C p.Tyr268His, in the MC4R gene in two unrelated patients with morbid obesity and evaluated the functional impact of these variants." (PMID 38003551, 2023). "The aim of this study was to establish the prevalence of MC4R mutations in a group of Turkish children and adolescents with morbid obesity." (PMID 28218067, 2017). "In humans, polymorphisms in melanocortin receptors are genetically linked with morbid obesity, while functional MC4R signaling is required for the beneficial effects of bariatric surgery." (PMID 26444289, 2015). "MC4R (melanocortin 4 receptor) gene was the first loci in which mutations were associated with morbid obesity in human beings." (PMID 23849767, 2013). "MC4R mutation analysis in a cohort of 77 children with morbid obesity identified previously unreported heterozygous mutations (P272L, N74I) in two patients inherited from their obese mothers." (PMID 23251400, 2012). "We describe two novel heterozygous mutations in the MC4R gene associated with early onset morbid obesity in childhood." (PMID 23251400, 2012). "Mutation in MC4R gene was found to be associated with morbid obesity in human beings." (PMID 25928419, 2015). "Hence, MC4R-Ko mice rapidly develop a dramatic obese phenotype consecutive to hyperphagia, while mutations in the MC4R gene have been associated to morbid obesity in humans." (PMID 21544212, 2011). "Furthermore, no deleterious mutations were found in genes known to cause morbid obesity such as leptin, leptin receptor, melanocortin 4 receptor, POMC, adiponectin and adiponectin receptor." (PMID 23300646, 2012).
Genetic obesity (17 papers, 2018 to 2025). "The only study reporting on phentermine treatment in patients with genetic obesity is a recent case series in 6 patients with heterozygous pathogenic MC4R variant." (PMID 39929239, 2025). "Concurrently, an ongoing trial (EMANATE, RM-493-035) is investigating the effect of setmelanotide on patients with suspected genetic obesity who carry variants in genes involved in the MC4R pathway." (PMID 40523925, 2025). "MC4R agonists that can cross the blood–brain barrier, and thus can be administered systemically, are already approved to treat rare forms of genetic obesity in humans, and obese individuals are more susceptible to develop MI and HF." (PMID 39612121, 2024). "The other study reporting on the effects of naltrexone-bupropion in genetic obesity, is a case report about 1 patient with a heterozygous pathogenic MC4R variant and an extensive medical history, including bariatric surgery and liraglutide treatment, with insufficient effect." (PMID 39929239, 2025). "Also in children with various types of genetic obesity, such as heterozygous and homozygous MC4R deficiency and 16p11.2 deletion syndrome, beneficial effects of liraglutide on body weight, cardiometabolic factors, and appetite regulation are reported." (PMID 39929239, 2025). "The predominant cause of non-syndromic genetic obesity often stems from mutations in the MC4R." (PMID 39125390, 2024). "Given the important role of MC4R in energy metabolism, MC4R is considered a potential drug target for the treatment of genetic obesity." (PMID 38567654, 2024). "The relevance of this study is due to the fact that mutational disorders of MC4R signaling are the most common form of genetic obesity in humans, but the effect of FGF21 on metabolic disorders caused by a decrease in MC4R functions has been little studied." (PMID 34943946, 2021). "Therefore, more structural and protein interaction studies are required to further clarify the roles of POMC-derived neuropeptides, MC3R, and MC4R in genetic obesity." (PMID 40001512, 2025). "Setmelanotide (Imcivree), an MC4R agonist marketed to treat certain forms of genetic obesity, resulted in similar responses with the combination of liraglutide, illustrating the idea that multiple MC4R agonists can increase the effect of liraglutide in inhibiting food intake and weight loss." (PMID 39007271, 2024). "Clarifying whether MRAP2 variants affect MC4R signaling could have important implications for patient care as the MC4R agonist, setmelanotide, has recently been licensed for use in chronic weight management for genetic obesity syndromes affecting the MC4R pathway." (PMID 39807633, 2025). "Setmelanotide is an anorexigenic medication and acts as a melanocortin-4 receptor (MC4R) agonist, it was approved by the FDA in the year 2020 for the management of genetic obesity." (PMID 38715796, 2024).
steatosis (16 papers, 2013 to 2025). Increased lipid within the cytoplasm of cells. "Similar to the plasma parameters reflecting MASH pathology, lipid accumulation in the liver, enhanced transcription of inflammation-related genes, and liver histopathology such as steatosis and lobular inflammation were also exacerbated in WD-fed MC4R-KO mice." (PMID 41266634, 2025). "Unlike in ZFD-fed mice, we found that hepatic FASN ablation ameliorated steatosis in ob/ob mice and, to a lesser extent, in Mc4r-KO mice." (PMID 37681411, 2023). "On the other hand, ballooning degeneration was not clearly observed in vehicle-treated MC4R KO mice, suggesting that WD-fed MC4R KO mice showed severe steatosis with weak inflammation in the liver." (PMID 31990961, 2020). "Our data also showed that GS-0976 at 4 and 16 mg/kg/day robustly lowered hepatic triglyceride content and improved steatosis histologically in WD-fed MC4R KO mice." (PMID 31990961, 2020). "Histological analysis demonstrated an increase of the hepatic steatosis and weak lobular inflammation in vehicle-treated MC4R KO mice fed with WD after 9-week treatment compared with lean control mice." (PMID 31990961, 2020). "We previously reported a unique histological structure or hCLS in the liver from MC4R-KO mice, where dead hepatocytes are surrounded by macrophages and suggested that hCLS promotes liver fibrosis during the progression from simple steatosis to NASH11." (PMID 28303974, 2017). "After 24 weeks, the livers from MC4R-KO mice fed control diet exhibited micro- and macrovesicular steatosis, ballooning degeneration, massive infiltration of inflammatory cells and pericellular fibrosis." (PMID 25816330, 2015). "We also confirmed similar results in the liver from MC4R-KO mice fed a WD for 4 weeks, when they showed simple hepatic steatosis." (PMID 24349208, 2013). "On the other hand, livers from MC4R-KO mice fed a WD exhibited micro- and macrovesicular steatosis, ballooning degeneration, massive infiltration of inflammatory cells, and marked pericellular fibrosis as we previously reported using a HFD." (PMID 24349208, 2013). "Collectively, MC4R-KO mice would provide a novel mouse model of NASH with which to investigate the sequence of events that comprise diet-induced steatosis and fibrosis in the liver." (PMID 24349208, 2013). "PFD markedly attenuated liver fibrosis in Western diet (WD)-fed melanocortin 4 receptor-deficient (MC4R-KO) mice without affecting metabolic profiles or steatosis." (PMID 29247356, 2018). "Next, we investigated whether treatment with OCA affects hCLS formation in MC4R-KO mice, since hCLS serves as the source of chronic inflammation-induced fibrosis during the progression from simple steatosis to NASH24,26." (PMID 29802399, 2018). "We histologically assessed the severity of liver injury with the NAFLD Activity Score (NAS); the WD-fed MC4R-KO mice showed a significantly greater level of steatosis, lobular inflammation, and hepatocyte ballooning than WT mice fed an SD, thus resulting in a higher overall NAS score." (PMID 28303974, 2017). "We previously reported the unique histological structure, hCLS, in the liver from MC4R-KO mice, where dead hepatocytes were surrounded by macrophages and suggested that hCLS serves as an origin of hepatic inflammation and fibrosis during the progression from simple steatosis to NASH25." (PMID 29402900, 2018). "PFD markedly attenuated liver fibrosis in western diet (WD)-fed MC4R-KO mice without affecting metabolic profiles or steatosis." (PMID 28303974, 2017). "Although the inflammation score was unchanged, the scores for steatosis and ballooning degeneration were decreased by EPA treatment, so that there was a significant reduction in NAS in EPA-treated MC4R-KO mice relative to control MC4R-KO mice." (PMID 25816330, 2015).
steatosis (continued). "Therefore, we considered chow-fed C57BL/6 mice, which are non-pathological, to be sufficient controls since WD-fed MC4R-KO mice are a well-established MASH model that shows both steatosis and fibrosis." (PMID 41266634, 2025). "Moreover, multiple liver tumors were observed in all of the MC4R–KO mice examined, while the livers from WT mice fed the standard diet presented mild steatosis with no tumor." (PMID 33681091, 2021). "Although the MC4R KO mice used in this study were independently created in our laboratory, the phenotype is similar with that of the WD-fed MC4R KO mice and reflects multiple aspects of pathophysiology of NASH patients such as liver injury, steatosis, and fibrosis." (PMID 31990961, 2020). "We histologically assessed the severity of liver injury with the NAFLD Activity Score (NAS); whereas 20 weeks of CANA treatment did not affect the steatosis score in WD-fed MC4R-KO mice, the scores for lobular inflammation and hepatocyte ballooning were reduced by CANA treatment." (PMID 29402900, 2018).
Cachexia (14 papers, 2008 to 2024). Severe weight loss, wasting of muscle, loss of appetite, and general debility related to a chronic disease. "Increased lean mass has been associated with MC4R mutations in humans and melanocortin blockade protects against lean mass loss in experimental cachexia in rodents." (PMID 22848742, 2012). "Additionally, our GSEA and doxorubicin treatment findings suggest that common mutations in the MC4R may be an important risk factor for increased sensitivity to cachexia, or possibly even cardiomyopathies induced by cardiotoxic drugs, such as doxorubicin." (PMID 28829041, 2017). "A similar study in cancer cachexia animal models has demonstrated reversal of cachexia with a peripherally administered MC4-R antagonist." (PMID 37128293, 2023). "Antagonism of MC4R has also been investigated to treat the metabolic and dietary components of cachexia and anorexia that lead to tissue wasting." (PMID 36943057, 2023). "Pharmacologic or genetic ablation of MC4R signalling reverses cachexia in multiple acute and chronic laboratory rodent models of cachexia." (PMID 32985801, 2020). "Earlier results indicated that subcutaneous administration of the small molecule MC-4R antagonist ML00253764 was efficacious in reducing cachexia in animals implanted with either a colorectal tumor or Lewis lung carcinoma." (PMID 19295909, 2009). "Moreover, another small molecule, PF-07258669, showed potent MC4R antagonism in an aged model of cachexia and is currently being investigated in clinical trials." (PMID 36943057, 2023). "As PBN CGRP neurons are inhibited by hypothalamic AgRP neurons and express MC4R, they may function as a downstream effector of hypothalamic‐mediated cachexia." (PMID 32985801, 2020). "MC4R activation is also critical to the initiation and maintenance of cachexia." (PMID 32725770, 2020). "In the light of the postulated role of the MC4R in development of cachexia as determined in different rodent studies, we hypothesized that heterozygotes for the 103Ile allele are more prone to develop cancer cachexia." (PMID 18377640, 2008). "However, these functional findings, which are compatible with an elevated MC4R function, cannot explain the possible protection against the development of cachexia." (PMID 18377640, 2008). "Based on recent literature demonstrating that LCN2 binds to hypothalamic MC4R15 and our observation that feeding behavior improves in Lcn2-KO mice during cachexia, we hypothesized that MC4R antagonism (or inverse agonism) would improve appetite during the development of cancer cachexia." (PMID 33824339, 2021). "More recently, a novel MC4R antagonist, TCMCB07, has been reported in preliminary studies to show efficacy and safety in rat renal and cancer‐induced cachexia, as well as in normal and companion dogs with cachexia." (PMID 32725770, 2020). "However, AHDS patients develop severe cachexia during their childhood, which, besides other mechanisms such as impaired T3 transport, could be the result of a disturbed interaction of the mutant MCT8 protein with MC4R." (PMID 39062808, 2024).